ZC3H11D (zinc finger CCCH-type containing 11D)
Synonyms: C12orf50; FLJ35821
Tractability: No criterion of Open Targets' tractability assessment is met for any kind of drug.
Gene: Protein-coding gene on chromosome 12 (87,980,035 to 88,034,037, reverse strand). Ensembl gene ENSG00000165805.
Gene Ontology:
Molecular function: protein binding
Biological process: poly(A)+ mRNA export from nucleus
Genetic constraint (gnomAD): Loss-of-function variants: 18 observed, 33.5 expected, observed/expected ratio (o/e) 0.54, 90% interval 0.37 to 0.8. The upper end of that interval is the gene's LOEUF score, 0.8, which puts it in group 3 of 6, group 1 being the genes least tolerant of losing a copy. Missense variants: 285 observed, 321.34 expected, observed/expected ratio (o/e) 0.89, 90% interval 0.8 to 0.98. Synonymous variants: 115 observed, 106.01 expected, observed/expected ratio (o/e) 1.08, 90% interval 0.93 to 1.27.
Homologues: Orthologues: chimpanzee C12H12orf50 (99% identical), macaque C11H12orf50 (96% identical), dog C12orf50 (88% identical), rabbit C12orf50 (86% identical), pig C12orf50 (86% identical), rat C7h12orf50 (83% identical), mouse 1700017N19Rik (82% identical), guinea pig C12orf50 (81% identical), zebrafish zc3h11a (19% identical). Paralogues in human: ZC3H11A (22% identical), ZC3H11B (21% identical), ZC3H11C (21% identical).